IL6 (interleukin 6)
Diseases named in the same sentence as IL6 in open-access papers (continued):
Sharing a sentence is not in itself a finding about the gene and the disease.
infection (continued). "This difference, observed in the current study, may be due to the type of patient samples used (serum vs nasal swabs) and suggest that the downregulation of the key cytokines, IL-2, IL-6, TNF-α, and IFN-γ, occurs in the nasopharyngeal milieu during the early infection." (PMID 36584119, 2022). "Strong inflammatory immune responses induced in ICU-admitted SARS-CoV-2-infected patients were characterized by high IL-6 and IL-17 levels, CCR6+ circulating (c)TFH17 cells in the blood, and anti-S IgG1 Abs with very low galactosylation levels that prevailed upon day 50 post-infection." (PMID 36713457, 2022). "Measuring both plasma and frontal IL-6 levels at the same time point (3 days post infection) may lead to the false impression that the levels are not predictive of each other—as plasma IL-6 levels may begin to fall as cortical levels are stable or increasing." (PMID 36380004, 2022). "Interestingly, dual species infections with P. gingivalis and S. oralis decreased the expression of IL-6, IL-12 (p40), and CCL5/RANTES compared to tissue without implants." (PMID 35203495, 2022). "IL-6 is widely used as a nonspecific indicator of immediate inflammatory response to infection." (PMID 35154511, 2022). "In conclusion, bone resorption induced by infection is elicited by enhanced expression of inflammatory cytokines and suppression of bone-related markers, and low-dose LTA restores LPS-induced bone resorption by inducing osteogenic differentiation of osteoblast through IL-6 and p38 signaling." (PMID 36293485, 2022). "Moreover, an increase in the expression of interleukin 6 (IL-6) and the receptor activator of nuclear factor kappa-Β ligand (RANKL), molecules involved in bone resorption, was observed following infection with oral bacteria from DM mice to non- DM mice, compared to transfer from non-DM mice." (PMID 36015357, 2022). "Since we have shown a significant association between IL-6 and TNF-α and functional outcomes in a group of patients without prior infection and other chronic inflammatory diseases, we can conclude that IL-6 and TNF-α are inflammatory markers of acutely ischemic brain injury." (PMID 36142524, 2022). "P-SEP, when combined with IL-6 and CRP, may be utilized as a negative predictive marker of EOS (NPV 97.2%, 95% CI: 93.3–101), especially in newborns at low to medium risk of infection." (PMID 36699313, 2022). "In our study, we observed that treatment with BCP-DHA, regardless of the presence of infection, negatively regulated the gene expression of IL-2, IL-6, IRF7, NLRP3, and TYK2, acting directly in NF-ĸB inhibition and the synthesis and activity of pro-inflammatory cytokines." (PMID 36357780, 2022). "These non-infectious inflammatory conditions may result, for example, in the release of cytokines such as interleukin-1 (IL-1), interleukin-6 (IL-6), tumor necrosis factor alpha (TNF-α), and gamma interferon (INF-γ), which mask those specific to the inflammatory response to infection." (PMID 35208167, 2022). "However, this is contrasted in the acute phase of infection, as an initial CD8 response moves to control viral replication of CHIKV in infected tissues, exhibiting an IFN-1 response with IL-4, IL-6, IL-7, CCL2, CCL4, CXCL10, and macrophage migration inhibition factor." (PMID 36016408, 2022). "RT-qPCR and Western blot analysis showed that the levels of IL-1β, IL-6, TNF-α, and iNOS increased and mRNA and protein levels of TGM2 decreased in liver tissues of HFD-fed mice in comparison to control mice, while opposite results were observed by the further infection of AAV8-anti-miR-9-5p." (PMID 35261562, 2021). "Routinely, viruses are often identified post-infection by pattern recognition receptors (PRRs), such as the inflammasome sensor NLRP3, which trigger the production of interferons (IFNs) and inflammatory cytokines (e.g., IL-1, IL-6, and TNF) and initiate a local/systemic response to infection." (PMID 34572585, 2021).
infection (continued). "The cytokine analysis of the child showed no significant increase in IL-6 and TNF, suggesting that the presence of a complex heterozygous CARD9 mutation may lead to decreased antifungal immunity and a susceptibility to TM infection." (PMID 34234782, 2021). "Our results showed that HTNV infection led to elevated cytokine production, including CXCL-1, CCL-5, IL-6, IL-12, TNF-α, and IFN-γ in Nlrc3−/− mice, and the levels of these cytokines peaked at 6 or 9 dpi; in comparison, WT mice had weaker cytokine responses throughout the infection process." (PMID 34335602, 2021). "IL-6 can issue a warning signal in response to both infection and noninfectious tissue damage which may be recognized by TLRs such as TLR2 and TLR4." (PMID 34336088, 2021). "We described time-dependent limits for the interpretation of five biomarkers (PSEP, PCT, CRP, WBC, and IL-6), which can be used as acceptable values in uncomplicated patients without infection after major surgery, including patients after kidney, liver, and pancreas transplantation." (PMID 33505219, 2021). "Furthermore, the initial proinflammatory cytokines, such as TNF-α, IL-6, and IL-1, produced in virus-infected cells may further activate NF-κB in adjacent cell populations to facilitate enhanced TMEV infection and replication." (PMID 34067536, 2021). "The levels of serum ALT, AST, liver IL-6, TNF-α, and IL-1β mRNA and liver pathological injury scores were further increased when pretreated with recombinant IL-27 in WT mice, but these levels were decreased in IL-27r−/− mice after CLP-induced severe infection compared to WT mice." (PMID 33564275, 2021). "Furthermore, we could only identify a trend or correlation between levels of IL-1β expression and those of IL-6, CCL3 and CCL4 in the very early infection phase (3 h) and at high bacterial loads (MOI = 1:1000)." (PMID 33652921, 2021). "Moreover, we observed that blocking IL-6 with a monoclonal antibody reduced the serum content of FFA in response to LPS, suggesting that IL-6 is involved in regulating lipolysis in response to infection." (PMID 34880245, 2021). "Also, TNF levels in BALF were significantly lower in Lysmcre-Btkfl/Y mice as compared to controls (p<0.05) 3 hours after D39 infection, whereas IL-6, CXCL1 and CXCL2 levels were not altered." (PMID 34552589, 2021). "The animals were sacrificed 96 hours and 2 weeks after infection, their lungs removed, macerated and the leukocytes analyzed by flow cytometry for the intracellular expression of IDO, AhR, and cytokines (IL-12, TNF-α, IL-1β, IL-6, TGB-β, and IL-10) by CD11c+ myeloid cells." (PMID 33936043, 2021). "The cytokines IL-6, IL1-ß, and TNF-α were the highest in the L. majorWT group and surprisingly not recapitulated in the L. majorR group; IL-6 in C57BL/6 mice was reported to be responsible for Th2 responses but not required to control the disease since IL-6 KO mice were able to control infection." (PMID 34972189, 2021). "Moreover, the expression of the cytokines IL-1β, IFN-γ, IL-6, TNF-α, and TGF-β was higher in HDV-∆L-HDAg mice than in HDV-WT at days 14 and 21 post-infection, in agreement with the increased liver damage observed at these time points; however, only the expression of TNF-α was significantly higher." (PMID 33925087, 2021). "Importantly, interleukin 6 (IL6), the primary inducer of STAT3-mediated hepcidin synthesis was significantly increased in the liver of WT-infected mice as compared to ΔspvB-infected mice at 3 days post-infection." (PMID 33475464, 2021). "IL-17 attracts neutrophils and monocytes to the infected tissue and induces production of cytokines like G-CSF and IL-6 that promote innate inflammation and chemokines such as the C-X-C motif chemokine ligand (CXCL) 1, CXCL2 and CXCL10, which recruit myeloid cells to the site of infection." (PMID 34205262, 2021). "Infection induces the expression of Il6 in WT mice but not in IFNγKO and iNOSKO mice." (PMID 34987496, 2021).
infection (continued). "In further trials, the TRIF-dependency of the IL-6 response was seen as early as 9 h after infection, a data point that clearly reflects an “early” response of initially-infected macrophages and not secondary infections within the monolayer." (PMID 34280250, 2021). "Interestingly, infected Lgals3–/– mice showed a drop in serum levels of Th1 and Th2 cytokines, including IFN-γ, IL-2, IL-5, IL-6, IL-10, and TNF, compared with WT mice; these differences were significantly pronounced at 14 days but ceased at 28 days post-infection." (PMID 35046919, 2021). "p.i., whereas it did not significantly reduce the enhanced IL-6 level post-infection." (PMID 34531740, 2021). "Interestingly, after Erk1/2 inhibition and infection of HIBCPP cells with the NmB strains, GO termini indicating an involvement of the NF-κB signalling pathway, a function of IL6, and a role of the tumour necrosis factor, were underrepresented compared to the untreated cells." (PMID 34863201, 2021). "The production of cytokines associated with pregnancy complications (premature birth and infections of the placental/fetal unit) was also increased in L. monocytogenes-infected trophoblasts (CCL2, CCL3, IL-8, CSF2, IL-1α/β, IL-1RA, IL-10, GM-CSF, IL-6, and TNFα)." (PMID 34367171, 2021). "Infection of cells lacking RIG-I or its adaptor MAVS fail to produce IL-6 or LTB4." (PMID 33680987, 2021). "Then, when there are no other clear laboratory indicators to indicate infection, one should be alert to the abnormal increase of IL-6, IL-8 and IL-10, which may indicate bacterial infection in the lungs." (PMID 34925324, 2021). "In addition, WT cells exhibited similar amounts of IL-1α, IL-1β, and TNF-α release with and without treatment, but lower levels of CXCL1 and IL-6 in infection supernatants." (PMID 33441602, 2021). "In addition, common clinical infection markers including procalcitonin, IL‐6 and C‐reactive protein are not specific for BSI, and neither can these distinguish between drug‐sensitive and drug‐resistant cases." (PMID 34331328, 2021). "Firstly, as the previous studies have reported, low pathogenic PRRSV-like CHsx1401 enhanced the production of pro-inflammatory cytokines including IL-1, IL-6 and TNF-α in PAMs and serum, which could inhibit infection of other pathogens through the activation of NF-КB pathway or STAT pathway." (PMID 33797313, 2021). "Furthermore, IL-6 stimulates the production of IL-21 by CD4 T cells and exerts a pro-survival role that can impact the effector/memory population in the context of infection." (PMID 34234771, 2021). "Though CB3-infected MDA5+/- mice have similar levels of inflammatory cytokines TNF-α, IFN-γ, IL-6, IL-17a, and IL-10 (data not shown) by day 7 following infection, CB3-infect MDA5+/- mice have greater systemic levels of both IFN-α and IFN-β compared to CB3-infected wt mice." (PMID 34804036, 2021). "The MALT1 inhibitor also did not affect the macrophage’s production of IL-6 and TNFα following L. pneumophila infection whether examined at the early 9-h time point or at 12, 24, and 48 h post infection." (PMID 34280250, 2021). "There are indications that SAA plays multiple roles in infection, but since the serum values were close to homeostasis and because no related cytokines (IL-1, IL-6, and TNFα) are differentially expressed in the liver, the observed changes were not likely to be a direct response to an infection." (PMID 34679062, 2021). "However, manipulation of these defenses and damage by the infection may lead to aberrant responses characterized by the unchecked release of pro-inflammatory cytokines such as IL-1α, IL-1β, TNFα, IFN-γ, and IL-6." (PMID 34440903, 2021). "Several reports show elevated levels of IL-6 in DHF/DSS and in both, and the discrepancy might be due to infection by different serotype." (PMID 34447698, 2021).
infection (continued). "Interestingly, GO terms related to TNF signalling and production of IL6 were lost specifically following Erk1/2 inhibition during infection with wild type Nm, which correlated with the reduced infection rates by the wild type in absence of Erk1/2 signalling." (PMID 34863201, 2021). "Aged macaques infected with H1N1 IAV had increased CXCL8 and IL-6 in the lung which, although not assessed in these studies, could facilitate greater neutrophil accumulation at the site of infection and potentially increase NET release." (PMID 34152253, 2021). "Notably, TNF‐α, IL‐1, and IL‐6 were not greatly induced in the intestine of the PDCoV single infection group and mock, whose level was significantly lower than that in both PRRSV infected groups." (PMID 33797313, 2021). "In contrast to other studies, we could not detect production of pro-inflammatory IL-6 upon in vitro infection of mDC and macrophages." (PMID 34122407, 2021). "Interestingly, in the absence of infection, we observed that the cells induced for HO-1 expression by hemin treatment presented a significant increase on IL-6 levels in comparison with the untreated cells (P = 0.0080)." (PMID 33912151, 2021). "Pre-treatment concentrations of IL-6 and NEFAs were elevated (p = 0.0005 and p = 0.0334, respectively), whereas haptoglobin concentrations were decreased among those animals that survived the infection, compared to those that did not (p = 0.0181)." (PMID 34073753, 2021). "Furthermore, in support of the less distinct wasting symptoms observed at day 6 following infection of mice from the clove EO versus the placebo cohort, lower TNF-α, IL-6, and MCP-1 concentrations were measured in serum samples taken from the former versus the latter." (PMID 33807493, 2021). "In our study, both IL-6 and SAA1 levels in sera of uninfected rhesus macaques were undetectable, whereas MTB infection resulted in a dose-dependent increase of these proteins, making these proteins sensitive markers of infection which can be detected by UCP-LFAs." (PMID 34943175, 2021). "Moreover, after removing individuals with genital inflammation from the analysis, 11 of the biomarkers remained significantly higher in the pre-infection group compared to the uninfected group (Fractalkine, GMCSF, ITAC, IL-1ß, IL-6, IL-7, IL-8, IL-21, MIP-1α, MIP-3α, and TNFα)." (PMID 33731158, 2021). "Here, we show that infected STAB-1 KO mice produced reduced serum, liver and splenic levels of IL-6 and TNF-α as compared to WT mice, suggesting that STAB-1 participates in the regulation of the inflammatory cytokine response in Lm-targeted mouse organs upon infection." (PMID 34374322, 2021). "In addition, to determine the viral load, submerged primary nasal epithelial cells were infected with 0.5 and 1 MOI HRV16, and HRV16 RNA at 72 h and LDH activity and IFN-β, IFN-λ1/3, IL-6 levels after HRV16 infection were measured at 24, 48, and 72 h post-infection." (PMID 34838080, 2021). "Among the selected cytokines or chemokines, IL-6, GM-CSF, CXCL1, CCL2, MIP-1α, MIP-2, IFN-α, and M-CSF (which are involved in acute inflammation and B cell maturation) were highly upregulated, although they exhibited transient inhibition at 1 day post-infection." (PMID 34068322, 2021). "Remarkably, we found higher TNF, IL-1β, IL-6, and IL-10 in lung homogenates of LysM-cre × Hif1αfl/fl mice when compared with Hif1αfl/fl control mice at 12 hours after inoculation; these differences were not present anymore at 40 hours after infection." (PMID 34393650, 2021). "In correlation with q-PCR data, no expression of IFN−α; TNF-α, and IL-6 could be observed upon infection of mDC, M1-, and M2 macrophages with SARS-CoV-2." (PMID 34122407, 2021). "This synergy, as well as the potent inhibition of both IL-6 and CXCL8 by an NSKI, suggest that targeting a few select kinases may be a potential new mechanism for anti-inflammatory therapy in the context of Pa infections in CF and other patients." (PMID 33524056, 2021).
infection (continued). "In the group without infection, IL6 on Day 1 showed the highest AUC." (PMID 34749673, 2021). "On day 6 following infection of mice from the placebo as opposed to the AC cohort, enhanced secretion of IL-6 and IFN-γ in MLN could be observed (p < 0.01 versus naive)." (PMID 34209438, 2021). "IL-2, IL-6 and TNF-α were all induced to significantly lesser extents in the cortexes of the infected TLR4mut mice compared with the infected TLR4WT mice at day 4 PI, but they were induced to similar levels in the brains of both genotypes by VEEV TC-83 infection at days 2, 6 and 8 PI." (PMID 33487119, 2021). "Likewise, we did not observe any correlation with other infection parameters such as procalcitonin (PCT) or interleukin (IL)-6 (data not shown)." (PMID 34934131, 2021). "Furthermore, IL-6 production was not significantly different in both wild-type and Nlrp3-/- BMDMs following ΔpknF mutant infection when compared to wild-type Mtb or complemented mutant strains." (PMID 34324582, 2021). "Moreover, infection of B.1.1.7 and B.1.351 resulted in significant elevation of several key inflammatory cytokines in K18-hACE2 mice, including TNF-α (lung), IL-1β (lung), IL-6 (lung and liver), IL-13 (liver), IFN-α (liver) and IFN-β (liver)." (PMID 34772941, 2021). "In our study, no significant change in IL-6 was found in the spleen after GNAstV infection; this might be related to large differences between individual goslings." (PMID 33647718, 2021). "In fact, higher TNF-α and IL-6 production was observed in vitro by stimulating, with inactivated yeasts of C. albicans, equal numbers of total red blood cell (RBC)-lysed cells from the bone marrow and the spleen of mice 7 days after the primary infection compared to cells from uninfected mice." (PMID 34975887, 2021). "Although it is not well understood if NF-κB and STAT3 are activated during HTLV-1 de novo infection, we speculate that NF-κB and STAT3 are activated, as NF-κB and STAT3-regulated inflammatory molecules, including IFN-γ, IL-1, TNF-α, IL-6 and CXCL10, are produced during HTLV-1 de novo infection." (PMID 33182552, 2020). "Loading of BMDM with Lb photo-inactivated by both Strategy #1 (orange bar) and Strategy #2 (red bar) significantly up-regulated IL-6 over their controls, i.e. no treatment (light gray) and infection with live Lb (dark gray and black bar), as true for TNF via Strategy #2." (PMID 33051524, 2020). "In 2019, another meta-analysis investigating IL-6 to differentiate between infection and non-infection in critically ill patients included six studies with 527 ICU patients, and reported a pooled sensitivity and specificity of 0.73 (95% CI, 0.61–0.82) and 0.76 (95% CI, 0.61–0.87), respectively." (PMID 33198109, 2020). "Due to the limitations of plasma transfusion, researchers are now focusing on developing neutralizing antibodies against virus particles along with immuno-modulation of cytokines like IL-6, Type I interferons (IFNs), and TNF-α that could help in combating the infection." (PMID 32849654, 2020). "Moreover, the infection model for histoplasmosis showed that the development of the IL-17 protective response required IL-6 but not the participation of IL-1 receptor signaling." (PMID 33425780, 2020). "To determine whether fenofibrate could exert the same effect in the absence of IL-10 in the single infection model, we assessed the levels of mRNA expression of the M1 markers IL-6, TNF-α and NOS2 in knock out mice." (PMID 33072115, 2020). "For instance, a higher expression of IL-1β and IL-18 may indicate that the infection is due to a gram + bacteria while IL-6 and TNF would have a higher expression in gram negative infections." (PMID 32655547, 2020). "Similarly, IL-6 and TNF-α gene expression results (respectively) corroborated those of iNOS with the lowest values consistently reported for cells preconditioned with nicotine prior to infection." (PMID 32370298, 2020).